CHMP5 (charged multivesicular body protein 5)
Description:
Probable peripherally associated component of the endosomal sorting required for transport complex III (ESCRT-III) which is involved in multivesicular bodies (MVBs) formation and sorting of endosomal cargo proteins into MVBs. MVBs contain intraluminal vesicles (ILVs) that are generated by invagination and scission from the limiting membrane of the endosome and mostly are delivered to lysosomes enabling degradation of membrane proteins, such as stimulated growth factor receptors, lysosomal enzymes and lipids. The MVB pathway appears to require the sequential function of ESCRT-O, -I,-II and -III complexes. ESCRT-III proteins mostly dissociate from the invaginating membrane before the ILV is released. The ESCRT machinery also functions in topologically equivalent membrane fission events, such as the terminal stages of cytokinesis and the budding of enveloped viruses (HIV-1 and other lentiviruses). ESCRT-III proteins are believed to mediate the necessary vesicle extrusion and/or membrane fission activities, possibly in conjunction with the AAA ATPase VPS4. Involved in HIV-1 p6- and p9-dependent virus release.
Synonyms: Vps60; C9orf83; SNF7DC2; CGI-34; HSPC177; PNAS-2; Spike
Tractability: Antibody: UniProt places it where antibodies can reach, with high confidence; its Gene Ontology location is reachable by antibodies, with high confidence. PROTAC: UniProt records ubiquitination sites on it; ubiquitination databases record sites on it; its protein half-life has been measured.
Gene: Protein-coding gene on chromosome 9 (33,264,017 to 33,282,071, forward strand). Ensembl gene ENSG00000086065.
Subcellular location: Cytoplasm, cytosol; Endosome membrane; Midbody
Subcellular location (Human Protein Atlas): Cytosol; Microtubules; Midbody
Pathways (Reactome):
Disease: Budding and maturation of HIV virion
Vesicle-mediated transport: Endosomal Sorting Complex Required For Transport (ESCRT)
Gene Ontology:
Molecular function: cadherin binding; protein binding
Biological process: autophagosome maturation; autophagy; cellular response to lipopolysaccharide; cellular response to muramyl dipeptide; late endosome to lysosome transport; midbody abscission; mitotic metaphase chromosome alignment; multivesicular body sorting pathway; nuclear membrane reassembly; nucleus organization; plasma membrane repair; regulation of centrosome duplication; regulation of mitotic spindle assembly; ubiquitin-dependent protein catabolic process via the multivesicular body sorting pathway; viral budding; viral budding from plasma membrane; viral budding via host ESCRT complex; ESCRT III complex disassembly; late endosome to vacuole transport via multivesicular body sorting pathway; membrane fission; multivesicular body assembly; multivesicular body-lysosome fusion; vesicle fusion with vacuole; vacuolar transport
Cellular component: amphisome membrane; autophagosome membrane; cytosol; extracellular exosome; kinetochore; kinetochore microtubule; lysosomal membrane; microtubule cytoskeleton; midbody; multivesicular body membrane; nuclear pore; plasma membrane; ESCRT III complex; nuclear envelope; endosome membrane; nucleus
Genetic constraint (gnomAD): Loss-of-function variants: 6 observed, 8.14 expected, observed/expected ratio (o/e) 0.74, 90% interval 0.4 to 1.44. That is too few expected variants to judge how well the gene tolerates losing a copy. Missense variants: 69 observed, 80.31 expected, observed/expected ratio (o/e) 0.86, 90% interval 0.71 to 1.05. Synonymous variants: 25 observed, 32.56 expected, observed/expected ratio (o/e) 0.77, 90% interval 0.56 to 1.07.
Homologues: Orthologues: chimpanzee CHMP5 (100% identical), macaque CHMP5 (100% identical), dog CHMP5 (99% identical), pig CHMP5 (99% identical), guinea pig CHMP5 (99% identical), mouse Chmp5 (99% identical), rat Chmp5 (99% identical), rabbit CHMP5 (93% identical), zebrafish chmp5b (84% identical), tropical clawed frog chmp5 (83% identical), zebrafish chmp5a (82% identical), Drosophila melanogaster Vps60 (63% identical), and 1 more. Paralogues in human: CHMP4A (31% identical), CHMP4B (30% identical), CHMP4C (26% identical), CHMP7 (24% identical), CHMP4BP1 (22% identical).
Diseases named in the same sentence as CHMP5 in open-access papers:
CHMP5 is named in the same sentence as 35 diseases in open-access papers, as found by Europe PMC text mining. Sharing a sentence is not in itself a finding about the gene and the disease. The quoted sentences say what the papers report.
leukemia (3 papers, 2024 to 2025). A malignant (clonal) hematologic disorder, involving hematopoietic stem cells and characterized by the presence of primitive or atypical myeloid or lymphoid cells in the bone marrow and the blood. "We took advantage of the MYC-GFP reporter to enumerate the specific impact of CHMP5 deficiency on leukemia-initiating cells (LIC) wherein LICs in ICN1-driven T-ALL express CD34 and MYC13,66." (PMID 40319015, 2025). "Charged multivesicular body protein 5 (CHMP5), a member of the multivesicular body, has been reported to serve as an anti-apoptotic protein to participate in leukemia development." (PMID 38664616, 2024). "Consistently, CHMP5 functions as an anti-apoptotic gene in leukemia." (PMID 38664616, 2024). "We show here however that CHMP5 did not control T-ALL cell death but instead promoted leukemia by enabling transcription of T-ALL genes." (PMID 38352301, 2024).
viral infection (3 papers, 2020 to 2024). "We found that several interactors of the host proteins are differentially expressed upon viral infection, are related to highly relevant pathways, and that the novel interaction of NUP98 with CHMP5 may activate an antiviral mechanism leading to disruption of viral budding." (PMID 32702714, 2020).
acute lymphoblastic leukemia (2 papers, 2024 to 2025). Leukemia with an acute onset, characterized by the presence of lymphoblasts in the bone marrow and the peripheral blood. "Here, using human and mouse T cell acute lymphoblastic leukemia (T-ALL) models, we identify an essential requirement for the endosomal sorting complex required for transport protein CHMP5 in T-ALL epigenetic and transcriptional programming." (PMID 40319015, 2025). "Using human and mouse models of T cell acute lymphoblastic leukemia (T-ALL), we identify an essential nuclear role for CHMP5, a cytoplasmic endosomal sorting complex required for transport (ESCRT) protein, in establishing and maintaining the T-ALL transcriptional program." (PMID 38352301, 2024).
lung carcinoma (2 papers, 2020). "Notably, some of the nine differential proteins (3HAO, ASAH1, CHMP5, FPRP, IBP3, MERTK, MUC18, NRP1, and PRIO) in tumor-forming rats have already been reported to be associated with lung cancer biomarkers/pathology/mechanisms or ovarian cancer metastasis." (PMID 32678190, 2020).
lymphoid leukemia (2 papers, 2024 to 2025). A malignant lymphocytic neoplasm of B-cell or T-cell lineage involving primarily the bone marrow and the peripheral blood. "We found that among cancers, lymphoid leukemias expressed the highest amount of CHMP5 protein." (PMID 40319015, 2025). "Interestingly, across hematological and solid cancers, lymphoid leukemias expressed the highest amount of CHMP5 proteins." (PMID 38352301, 2024).
ovarian carcinoma (2 papers, 2020 to 2024). A malignant neoplasm originating from the surface ovarian epithelium. "For ferroptosis markers (CHMP5 and DDIT3), CHMP5 and DDIT3 protein expressions were notably down-regulated in high-grade ovarian cancer tissues." (PMID 38178187, 2024). "The clinical samples also confirmed that the levels of immune microenvironment markers (CD1α and CD4) and ferroptosis markers (CHMP5 and DDIT3) were lower in high-grade ovarian cancer tissues." (PMID 38178187, 2024).
T-cell acute lymphoblastic leukemia (2 papers, 2024 to 2025). Acute lymphoblastic leukemia of T-cell origin. "Here the authors report that nuclear CHMP5 promotes T cell acute lymphoblastic leukemia initiation and maintenance in part through regulating epigenetic and transcriptional events." (PMID 40319015, 2025).
acute myeloid leukemia (1 paper, 2024). Acute myeloid leukemia (AML) is a group of neoplasms arising from precursor cells committed to the myeloid cell-line differentiation. "Silencing CHMP5 elevates the content of caspase-8 and caspase-9 in acute myeloid leukemia cells, indicating that CHMP5 is able to prevent cell apoptosis." (PMID 38664616, 2024).
colorectal cancer (1 paper, 2023). A primary or metastatic malignant neoplasm that affects the colon or rectum. "Furthermore, CHMP5 knockdown in human HCT116 colorectal cancer cells selectively inhibits Rab11a‐exosome production." (PMID 36872252, 2023).
glioma (1 paper, 2022). A benign or malignant brain and spinal cord tumor that arises from glial cells (astrocytes, oligodendrocytes, ependymal cells). "It has been reported that in CHMP5-deficient glioma cells, both the granzyme B/perforin apoptotic pathway and the apoptosis-inducing factor-mediated necrosis pathway are activated, independently of the intrinsic and extrinsic apoptotic pathways." (PMID 36518671, 2022).
hepatoma (1 paper, 2021). "The interaction between BSEP and CHMP5 was validated via co-immunoprecipitation using three hepatoma cell lines, Hep G2, Huh-7, and Mahlavu." (PMID 33750401, 2021).
Sepsis (1 paper, 2024). Sepsis is defined as life-threatening organ dysfunction caused by a dysregulated host response to infection. "The volcano plot and heatmap indicated that JAK3, CHMP5 and IFNAR1 were upregulated while CASP8, VDAC2, FASLG, JAK1, STAT4 and BCL2 were downregulated in sepsis." (PMID 38894720, 2024).
tuberculosis (1 paper, 2025). A chronic, recurrent infection caused by the bacterium Mycobacterium tuberculosis. "A bioinformatics study utilizing blood microarray transcriptional datasets identified three ferroptosis-related genes-CHMP5, SAT1, and ZFP36-as potential diagnostic biomarkers for tuberculosis (TB)." (PMID 40565608, 2025).
cancer (9 papers, 2021 to 2025). A tumor composed of atypical neoplastic, often pleomorphic cells that invade other tissues. "Both in vitro and in vivo, human cancer cells (PANC1 and HepG2) become more susceptible to ferroptosis mediated by lipid peroxidation when CHMP5 is knocked down via RNA interference." (PMID 39200152, 2024). "Our Chmp5 knockdown studies in both flies and human cancer cell lines suggest that Rab11a‐exosomes perform specialised physiological and pathological functions." (PMID 36872252, 2023). "This is in agreement with a recent study showing that knock down of CHMP5 or CHMP6 sensitizes cancer cells to ferroptosis." (PMID 33335287, 2021). "Therefore, future studies to elucidate CHMP5 function have the potential to advance our understanding of transcriptional addiction mechanisms in cancer cells." (PMID 40319015, 2025). "Therefore, future studies to elucidate CHMP5 function in these malignancies have the potential to significantly advance our understanding of transcriptional addiction mechanisms in cancer cells." (PMID 38352301, 2024). "Whether CHMP5 also regulates the BRD4-p300-MYC axis and super-enhancers in these cancers remains to be determined." (PMID 40319015, 2025). "Whether CHMP5 also regulates AML, in which the BRD4-dependent MYC super-enhancer is also a therapeutic vulnerability, and other cancers that display a p300-BRD4 dependency remains to be determined." (PMID 38352301, 2024). "Yet, non-membrane remodeling roles of CHMP5 in either normal or cancer cells remain largely unexplored." (PMID 38352301, 2024). "CHMP5 or CHMP6 confers resistance to ferroptotic PANC1 and HepG2 human cancer cell death." (PMID 36330465, 2022).
infection (5 papers, 2016 to 2024). The state of being infected such as from the introduction of a foreign agent such as serum, vaccine, antigenic substance or organism. "Our analysis demonstrates that Tsg101 interacts with both upstream complex Hrs and with downstream complex proteins, EAP45 (ESCRT-II), CHMP6 (ESCRT-III) and CHMP5 (ESCRT-III), and CHMP5 and CHMP6 proteins associate with KSHV (glycoprotein gB) particles early during infection." (PMID 27764233, 2016).
neurodegenerative disease (1 paper, 2022). A disorder of the central nervous system characterized by gradual and progressive loss of neural tissue and neurologic function. "CHMP5 has not been reported in previous ALS related research, and SLC38A1 is a main transporter of glutamine and has been reported as a positive regulator of mTOR complex 1 (mTORC1), which is closely connected with autophagy and plays an essential role in many neurodegenerative diseases." (PMID 35873477, 2022).
CHMP5 also shares sentences with these, for which no sentence is quoted: T-cell leukemia (2 papers); amyotrophic lateral sclerosis (1); bacterial infections (1); cholestasis (1); cognitive deficits (1); colon cancer (1); COVID-19 (1); dementia (1); diphtheria (1); endometrial cancer (1); infant botulism (1); infectious disease (1); osteoarthritis (1); pancreatic cancer (1); Parkinson disease (1); primary bone cancer (1); prostate carcinoma (1); tetanus (1); tumor (1).